IL6R (interleukin 6 receptor)
Diseases named in the same sentence as IL6R in open-access papers (continued):
Sharing a sentence is not in itself a finding about the gene and the disease.
tumor (continued). "Our finding is consistent with a previous report on MR16-1, a rodent analog of tocilizumab and a commercial humanized recombinant IL-6R mAb, that enhanced anti-tumor activity by eliminating MDSCs." (PMID 30083161, 2018). "A recent study has shown that blocking of the IL-6 receptor (IL-6R) or TGF-β in tumor-bearing mice, decreases both monocytic and granulocytic MDSC subsets, alongside a reduction in tumor growth and improvement in T-cell function." (PMID 30298121, 2018). "This implies that the 12% fractional occupancies predicted by our model leaves room for increases in proportion of bound IL-6R and more aggressive tumor growth when endothelial cells add to the amount of IL-6 available in the tumor microenvironment." (PMID 29351275, 2018). "This study presents role of IL-6/IL-6R-MAO-A signalling axis in invasion/angiogenesis in hypoxic tumour environment and highlights this signalling as critical target for cancer therapy." (PMID 29695771, 2018). "We have developed a preliminary mathematical model of this experimental paradigm and our early results show high fractional occupancies of IL-6R lead to even greater interdependencies among IL-6, tumor growth dynamics and the tumorigenic potential of CSCs." (PMID 29351275, 2018). "After treatment there is an 80-90% decrease in the fraction of IL-6R occupied by IL-6 on tumor cells." (PMID 29351275, 2018). "In subcutaneous xenograft models, IL6R knockdown resulted in obvious growth delay of M1 cells, while IL6R overexpression led to significantly increased tumour growth of N2 cells." (PMID 29258522, 2017). "The combination with IL-6R antibody decreased this activation and significantly reduced the tumor volume compared to the sorafenib monotherapy." (PMID 28903416, 2017). "Collectively, this work has shown that LEPR signaling is able to positively impact on several key tumor-promoting phenotypes that are also influenced by other IL-6R-related receptors, such as IL-6R itself and G-CSFR." (PMID 29212170, 2017). "We used Cutoff Finder to determine a cutoff point and stratified patients into two groups and found that high-expression of IL-6R mRNA in tumor tissues was a positive prognostic factor for overall survival." (PMID 28821817, 2017). "It is likely that DPP4 regulate the tumor cell growth through generation of chemokines and cytokines, such as IL-6R." (PMID 27936466, 2017). "To evaluate the correlation between tumor IL-6R and gp130 and the outcome of patients, we used a tissue microarray (TMA) containing 77 specimens prepared from the invasive front of HNSCC tumors." (PMID 29245982, 2017). "IL-6 and IL-6R have been shown to promote tumor growth, and we previously identified the IL6R gene as one of the inflammation-related genes in a 14-gene prognostic signature in children with high-risk tumors lacking MYCN amplification." (PMID 29207662, 2017). "This circuit can also be triggered by other extrinsic signals from the tumor microenvironment or intrinsic cancer cell signals (such as oncogene activation and tumor suppressor inactivation), which activate IL-6R or STAT3." (PMID 28388577, 2017). "The IL-6/IL-6R/STAT3 pathway mediates interactions between tumor cells and the TME and contributes to the development of drug resistance." (PMID 28928376, 2017). "Measurement of human interleukin 6-receptor (huIL-6R) in final sera of mice revealed huIL-6R concentrations between approx. 10 – 150 ng/ml that correlated with explanted tumor sizes." (PMID 29100408, 2017). "We found that high IL-6R expression in the invasive front of the tumor correlated with poor overall survival (log rank test, p=0.0217)." (PMID 29245982, 2017). "IL-6 is considered a mediator of monocyte-mediated proliferation of tumor cells through its binding to the IL-6 receptor (IL-6R)." (PMID 29207662, 2017).
tumor (continued). "Compared with M1-control-shRNA, knockdown of IL6R significantly suppressed intracranial tumour growth and resulted in an increase in survival (median survival: 39 ± 1.6 days vs. 119 ± 4.4 and 108 ± 2.2 days, respectively)." (PMID 29258522, 2017). "Immunohistochemical analysis showed that IL-6, IL-6R and gp130 are highly expressed in tumor sections of the control NOD/SCID mice, while in sgp130-treated mice, their expression levels are significantly lower." (PMID 27080032, 2016). "Alteration of IL6R gene transcription is correlated with tumor grade in HCC, and in the initial processus of hepatocellular transformation, this receptor participates in hepatocellular transformation." (PMID 26380295, 2015). "The Western blot analysis also revealed the similar trend of IL-6, IL-6R and gp130 during tumor growth." (PMID 26525581, 2015). "Age, FIGO stage, histological type, residual tumor at the time of surgery, “high” IL-6 expression and “high” IL-6R expression were entered in this model." (PMID 25658637, 2015). "Blocking IL-6 signalling with an anti-interleukin-6 receptor antibody or inhibiting IL-6 trans-signalling with TGF-β has also been shown to suppress tumour progression in colon cancer." (PMID 26446703, 2015). "Subsequently, all the factors were down-regulated, and RT-PCR indicated that the expression ratios of seven weeks/five weeks of IL-6, IL-6R, and gp130 in tumor growth decreased by 0.43-fold, 0.47-fold, and 0.33-fold, respectively." (PMID 26525581, 2015). "Based on this observation, we treated HER2-positive, PTEN deleted, tumor xenografts with a combined treatment of trastuzumab and tocilizumab, a monoclonal antibody directed against IL-6R." (PMID 26932376, 2014). "Confocal microscopy showed that MDSCs in the spleen, primary tumor sites and lung expressed increased levels of Adam17 and IL-6Rα on their surfaces in 4T1 cell-bearing mice compared to those in EMT6 cell-bearing mice." (PMID 24021059, 2013). "To investigate which cells in the tumor microenvironment provide soluble IL-6Rα, we measured levels of soluble IL-6Rα secreted from ex vivo-cultured splenic MDSCs from naïve, EMT6 cell-bearing, and 4T1 cell-bearing mice and 4T1 cancer cells." (PMID 24021059, 2013). "In this study, we showed that metastasizing cancer cells induced higher MDSCs infiltration and prompted them to secret exaggerated IL-6 as well as soluble IL-6Rα, which, in turn, triggered a persistent increase of pSTAT3 in tumor cells." (PMID 24021059, 2013). "The sizes of tumor xenografts harvested from IL-6R-expressing C666-1 were on average 64% larger than the tumor xenografts established from control C666-1 cells." (PMID 23658720, 2013). "To confirm the expression of Adam17 and IL-6Rα by MDSCs in vivo, we analyzed spleen tissues, primary tumor masses and metastatic lesions in the lungs from 4T1 cell-bearing mice." (PMID 24021059, 2013). "We therefore examined the expression of IL-6R in NPC tumor biopsies using a tissue microarray (TMA) containing 7 normal nasopharyngeal tissues and 45 NPC specimens." (PMID 23658720, 2013). "Among soluble factors released from astrocytes, IL-6 was most likely responsible for tumor growth, because only the expression of IL-6R on tumor cells was up-regulated during the activation with astrocytes." (PMID 23271367, 2012). "Among the receptors for soluble factors released from astrocytes, only IL-6 receptor (IL-6R) on tumor cells was up-regulated during the activation with astrocytes." (PMID 23271367, 2012). "Although IL-6 was expressed in the cytoplasm of the cancer cells, IL-6R was expressed in tumour cell membranes." (PMID 20823887, 2010). "Tumor/TV was markedly reduced in Ki26894-treated mice, which is consistent with the serum levels of soluble human IL-6R, a surrogate marker for a human MM tumor burden, in MM-bearing SCID-rab mice." (PMID 20360846, 2010).
tumor (continued). "Notably, genes implicated in oncogenic signaling and tumor progression, including GNB4, EGF, MYB, IL6R, ANGPT4, and ITGB8, were consistently downregulated in both BxPC3 and SW1990 cells following PCDH1 silencing." (PMID 41602375, 2026). "Furthermore, expression analysis based on scRNA data revealed that IL-6 is predominantly expressed by fibroblasts, tumour cells, and macrophages, while IL-6R and IL6ST are mainly expressed in tumour cells, CAFs, and various immune cells." (PMID 39858048, 2025). "Increasing investigation into the inflammatory microenvironment and immune response of these tumors presents new therapeutic possibilities and promising alternatives for tumor control, such as the use of anti-IL-6R, anti-VEGF agents and immune checkpoints inhibitors." (PMID 40433410, 2025). "Anti-IL-6R monoclonal antibodies (e.g., tocilizumab) reduce tumor invasion and cystic volume." (PMID 40433410, 2025). "When comparing mice treated with the TGFβ vaccine to those receiving the vaccine alongside an anti-IL-6R antibody, we found that inhibition of IL-6 signaling reduced overall T-cell infiltration within the tumor, including decreases in CD4+ T cells, CD8+ T cells and regulatory T cells." (PMID 39653766, 2025). "Notably, targeted inhibition of interleukin-6 receptor (IL-6R), which is highly expressed in ALDHhigh ECSCs, leads to a marked reduction in tumor cell growth, highlighting the critical role of IL-6 signaling in CSC maintenance." (PMID 41373619, 2025). "Based on the different IL-6R mRNA levels in SW480 and HT-29 cells, the tumor responses to anti-IL-6R antibody treatment were compared between xenografts of SW480 and HT-29 cells in NU/NU mice, including tumor growth, invasiveness in vivo, and the underlying mechanism." (PMID 38256960, 2024). "Hopefully, these trials will soon provide insights into the efficacy and safety of IL-6/IL-6R neutralization as a therapeutic strategy for reactivating the T cell compartment and combating tumor development in patients refractory to first-line immune checkpoint inhibitor-based therapies." (PMID 39281678, 2024). "Moreover, combined PD-L1 and IL-6R blockade caused tumor regression in pre-clinical models of solid tumors, improving CTL anti-tumor responses compared with anti-PD-L1 alone." (PMID 39281678, 2024). "In the present study, we attempted to further investigate whether IL-6R expression level is the important predictor for the tumor response of CRC to anti-IL-6R antibody treatment." (PMID 38256960, 2024). "Moreover, blockade of EGFR/ERK/NFκB and EGFR/PI3K/NFκB signaling not only decreases IL6 and IL6R-associated chemoresistance in OC but also, when combined with an anti-IL6 antibody (Tocilizumab), potentiates the anti-tumor effect." (PMID 39766086, 2024). "These successful experiments supported the idea that IL-6/IL-6R neutralization may by exploited to reactivate the T cell compartment and counteract tumor development." (PMID 39281678, 2024). "We hypothesized IL-6R expression of CRC could be the key factor to influence the tumor response to anti-IL-6R antibody therapy." (PMID 38256960, 2024). "From the perspective of precision medicine, tumor response to anti-IL-6R antibody therapy could be predicted on the basis of IL-6R expression levels." (PMID 38256960, 2024). "More recently, we further demonstrated that injection therapy of anti-IL-6R antibodies suppressed the tumor growth of SW480 xenograft and attenuated the proliferation marker Ki-67, along with down-regulating JAK/STAT3, PI3K/AKT, and MEK/ERK-1/-2 signaling pathways." (PMID 38256960, 2024). "Also, the inhibitory effect of anti-IL-6R antibodies on tumor growth in SW480 xenografts was more powerful than in HT-29." (PMID 38256960, 2024). "Overall, blockade of the IL‐6/IL‐6R pathway phenocopied O‐glycan truncation in tumor cells ex vivo." (PMID 37452653, 2024).
tumor (continued). "In addition, KPT tumor organoids showed increased IL-6 receptor (IL6r) expression, while expression of their IL-11 receptor (IL11r) remained unaltered." (PMID 39128004, 2024). "Moreover, the maximum killing by CTLs is observed in O‐glycan‐truncated tumor cells treated with both anti‐IL‐6R and anti‐PD‐1 antibodies." (PMID 37452653, 2024). "Our previous studies showed that anti-IL-6R antibodies potentially inhibited tumor growth and invasiveness in vitro and in vivo through interfering with IL-6 signaling transduction in IL-6R expressing CRC cell lines, including Erk-1/-2, STAT3 and AKT phosphorylation/activation." (PMID 38256960, 2024). "TGF-β and IL6R are immunosuppressive factors in the tumor microenvironment, so depleting these soluble factors could help improve the efficacy of cancer immunotherapy treatments, such as immune checkpoint blockade and CAR-T therapy." (PMID 38513100, 2024). "However, evidence is more limited for the role of IL6 and its cognate receptor, IL6R, within the tumour epithelium and microenvironment." (PMID 39766336, 2024). "At the endpoint (week 7), upon sequential PD-L1 and IL-6R immunotherapy, splenic lymphocytes of the shMCT-1 tumor-bearing mice increased more CD4(+) helper T cells and CD19(+) B cells but unchanged CD8(+) CTLs and NK cells when compared with those bearing scramble tumors and treated by isotype IgG." (PMID 38505617, 2024). "Cycles of IL-6R/STAT3 signaling may promote metastatic spread by increasing the likelihood of favorable phenotypes detaching from the primary tumor and surviving long enough to colonize distant tissues." (PMID 38141171, 2024). "Moreover, inhibiting their signaling with anti-IL-6R and CSF1Ri kept CD14+ cDC2 frequencies equal to tumor-free conditions, underlining IL-6 and M-CSF as dominant drivers of tumor-induced CD14+ cDC2s." (PMID 38242119, 2024). "Furthermore, the expression levels of IL-6R, STAT3, PD-L1, and VEGF-A, key molecules associated with tumor formation, were examined in the treated CT-26 cells to study the effects on tumor proliferation." (PMID 38725047, 2024). "Furthermore, they showed that IL-6 promoted engraftment and dissemination of IL-6R expressing tumour cells in a mouse model, as well as promotion of MYC-driven lymphomagenesis." (PMID 38633747, 2024). "Because cancer stemness largely contributes to the tumor metastasis and recurrence, we aimed to identify whether the blockade of MCT-1 and IL-6R can render these effects and to understand the underlying mechanisms that govern the process." (PMID 38505617, 2024). "Repurposing tocilizumab (IL-6R monoclonal antibody) may be a strategy to treat TNBC that overexpress IL-6R by reducing the chromosomal instability of tumor cells." (PMID 36765683, 2023). "Positive expression of IL6R staining was detected in the tumour cell cytoplasm and membrane." (PMID 37199043, 2023). "Therefore, IL-6/IL-6R is a target for cancer therapies by using antagonists, monoclonal antibodies, or shRNA, suppressing cancer stem cells, colony formation, and tumor development." (PMID 36794014, 2023). "When scores for tumour cytoplasmic and membrane IL6R were combined to form three groups of low for both, high for one marker and high for both markers, a significant association with reduced CSS in the high both group was observed (HR = 1.758, 95% CI: 1.329–2.324, log rank p < 0.001)." (PMID 37199043, 2023). "This indicates that CAFs may influence tumor cells and other cell types via the IL-6/IL-6R pathway and a wide range of outgoing signals." (PMID 38239853, 2023). "It has been suggested that BACE1 could alter cancer progression by changing the tumor microenvironment, activating STAT3 signaling via IL-6R, and subsequently maintaining tumor-promoting macrophages." (PMID 37511924, 2023).
tumor (continued). "Furthermore, the IL-6R-neutralizing antibody inhibited STAT3 activation induced by MpMDCS stimulation in SBC-3 cells, suggesting that MpMDCS also enhances tumor proliferation via STAT3 activation induced by the IL-6/IL-6R signaling pathway." (PMID 36961655, 2023). "In tumor-bearing mice, CTL-specific IL6R deficiency is sufficient to improve anti-PD-L1 activity." (PMID 36599350, 2023). "claimed that depletion of UCA1 curbed malignant progression of MM by up-regulating miR-331-3p abundance and reducing the abundance of IL6R, suggesting that miR-331-3p might function as a tumor suppressor and thus hinder the malignant phenotypes of tumor." (PMID 37173768, 2023). "Indeed, combined ICI and anti-IL-6 or anti-IL-6R Abs have been reported to potentially enhance anti-tumor immunity or reduce immune-related toxicity in preclinical and clinical studies." (PMID 38469154, 2023). "Tocilizumab, an IL-6R antibody, could induce the production of tumor immunity-stimulating factors, such as IL-12, IL-1β, and anti-tumor cytokines, such as TNF-α, and IFN-γ." (PMID 35681617, 2022). "Due to IL-6’s pleiotropic nature, it has also been shown to play critical roles in tumour growth, angiogenesis, and metastasis of different cancer types by activating signalling pathways after assembly and dimerization with its receptor IL-6R and glycoprotein 130 (gp130)." (PMID 36439165, 2022). "Alternative strategies might also include pH-responsive binders to only allow binding of the mAb to IL-6R within the acidified tumour microenvironment, or alternatively masking this binding unit with an anti-idiotypic binder connected via a cleavable linker." (PMID 36439165, 2022). "The observation of staining Patterns 1 and 3 in human IBC specimens raised the intriguing possibility that in certain IBC tumors, IL-6 may be supplied in trans from one tumor cell clone to a second clone expressing IL-6R." (PMID 35565421, 2022). "IL-6 also could induce tumor cell growth, metastasis, and angiogenesis through IL-6R-mediated pathways." (PMID 35513871, 2022). "Previous studies have focused on STAT-3, IL-6R and IL-6 pathways as enhancers of tumor progression." (PMID 35703345, 2022). "Importantly, the IL6 trans-signaling pathway is involved in most of the harmful effects of IL-6 in chronic inflammatory diseases and in cancer where it leads to switch on IL6-signaling in tumor or stromal cells expressing zero or low level of IL6R." (PMID 34576335, 2021). "Notably, high levels of tumor IL-6R and serum IL-6 expression are strongly correlated with poor survival of patients with HNSCC." (PMID 34689150, 2021). "However, blocking IL-6 signals by anti-IL-6R antibody therapy was sufficient to suppress tumor formation in anti-IL6-R-treated Apcmin/+Ripk3-/- mice." (PMID 33996591, 2021). "IL-6R participated several important pathways in tumor development and chemo-resistance." (PMID 33789615, 2021). "Furthermore, we used in vitro media swap studies to characterize tumor, fat, and muscle crosstalk via IL6R trans-signaling in PDAC cachexia." (PMID 33851955, 2021). "IL-6 mediates its activity through IL-6R expressed on tumour cells and GAMs." (PMID 33803414, 2021). "This novel cytokine targets a receptor upregulated in tumor cells (IL-6Rα) via the pepL ligand." (PMID 34209203, 2021). "Interestingly, the expression of membrane-bound IL6R isoform was moderately upregulated in most tumor types although the total expression IL6R was largely downregulated." (PMID 34576335, 2021). "In addition, STarMirDB analysis identified 9 miRNAs targeting IL6R Exon 9 (LogitProb ≥ 0.5) in at least 1 tumor type." (PMID 34576335, 2021). "Indeed, the application of anti-IL-6 and anti-IL-6R tocilizumab reduced hypoxia- or TMZ-induced autophagy and caused significant tumour cell apoptosis." (PMID 33803414, 2021). "TAMs secreting IL-6, activating IL-6R/STAT3/miR-204-5p pathway of tumor cells." (PMID 34095111, 2021).